SEPTIN9 (septin 9)
Description:
Filament-forming cytoskeletal GTPase (By similarity). May play a role in cytokinesis (Potential). May play a role in the internalization of 2 intracellular microbial pathogens, Listeria monocytogenes and Shigella flexneri.
Synonyms: KIAA0991; MSF; SEPT9; MSF1; PNUTL4; AF17q25; SeptD1; SINT1
Tractability: Small molecule: a structure with a bound ligand is known; a high-quality ligand is known. PROTAC: ubiquitination databases record sites on it; a small molecule that binds it is known.
Gene: Protein-coding gene on chromosome 17 (77,280,569 to 77,500,596, forward strand). Ensembl gene ENSG00000184640.
Subcellular location: Cytoplasm, cytoskeleton
Subcellular location (Human Protein Atlas): Actin filaments; Cytokinetic bridge; Microtubules; Primary cilium
Gene Ontology:
Molecular function: cadherin binding; protein binding; GTPase activity; molecular adaptor activity; GTP binding
Biological process: cytoskeleton organization; positive regulation of non-motile cilium assembly; cytoskeleton-dependent cytokinesis; intracellular protein localization
Cellular component: actin cytoskeleton; axoneme; cilium; intercellular bridge; microtubule; microtubule cytoskeleton; non-motile cilium; perinuclear region of cytoplasm; septin complex; stress fiber; cell division site; cytoplasm; septin ring; cytoskeleton
Genetic constraint (gnomAD): Loss-of-function variants: 12 observed, 49.83 expected, observed/expected ratio (o/e) 0.24, 90% interval 0.15 to 0.39. The upper end of that interval is the gene's LOEUF score, 0.39, which puts it in group 1 of 6, group 1 being the genes least tolerant of losing a copy. Missense variants: 645 observed, 798.26 expected, observed/expected ratio (o/e) 0.81, 90% interval 0.76 to 0.86. Synonymous variants: 329 observed, 327.42 expected, observed/expected ratio (o/e) 1, 90% interval 0.92 to 1.1.
Gene-disease validity (ClinGen):
ClinGen rates the evidence that SEPTIN9 causes each of these diseases.
neuralgic amyotrophy (autosomal dominant): Moderate. Neuralgic amyotrophy (NA) is an uncommon disorder of the peripheral nervous system characterized by the sudden onset of extreme pain in the upper extremity followed by rapid multifocal motor weakness and atrophy and a slow recovery in months to years.
Homologues: Orthologues: chimpanzee SEPTIN9 (99% identical), macaque SEPTIN9 (95% identical), guinea pig SEPTIN9 (91% identical), dog SEPTIN9 (90% identical), mouse Septin9 (90% identical), pig SEPTIN9 (90% identical), rat Septin9 (88% identical), tropical clawed frog septin9 (70% identical), zebrafish septin9a (61% identical), zebrafish septin9b (45% identical), Drosophila melanogaster Septin2 (22% identical), Caenorhabditis elegans unc-61 (22% identical). Paralogues in human: SEPTIN3 (45% identical), SEPTIN12 (35% identical), SEPTIN7 (27% identical), SEPTIN5 (26% identical), SEPTIN2 (25% identical), SEPTIN1 (24% identical), SEPTIN10 (24% identical), SEPTIN6 (24% identical), SEPTIN11 (23% identical), SEPTIN8 (23% identical), SEPTIN14 (22% identical), TMEM250 (4% identical).
Diseases named in the same sentence as SEPTIN9 in open-access papers:
SEPTIN9 is named in the same sentence as 126 diseases in open-access papers, as found by Europe PMC text mining. Sharing a sentence is not in itself a finding about the gene and the disease. The quoted sentences say what the papers report.
colorectal cancer (124 papers, 2008 to 2026). A primary or metastatic malignant neoplasm that affects the colon or rectum. "This meta-analysis aimed to evaluate the comparative diagnostic efficacy of Syndecan-2(SDC2) and Septin-9(SEPT9) in the early detection of colorectal cancer (CRC)." (PMID 39717169, 2024). "Although some septins are associated with the advancement of kidney fibrosis, SEPTIN9 specifically has been implicated in a host of disease pathologies, such as prostate cancer, colorectal cancer, liver fibrosis and T2DM." (PMID 33933144, 2021). "Using methylated Septin 9—an established biomarker for colorectal cancer (CRC)—as a case study, we evaluated the analytical and clinical performance of the assay." (PMID 40283264, 2025). "The approval for using plasma-derived methylated Septin9 as a colorectal cancer screening tool has been granted by the U.S. Food and Drug Administration (FDA)." (PMID 41487574, 2025). "As a proof of concept, a STEM-PCR-LFD assay was applied to detect methylated Septin 9, a biomarker for colorectal cancer." (PMID 40283264, 2025). "The hypermethylation of Septin9 in ctDNA is observed in various cancers, including colorectal cancer and lung cancer." (PMID 38892831, 2024). "It is known that the current domestic study of Septin9 gene methylation test screening for colorectal cancer only included more than 400 participants." (PMID 39544297, 2024). "The clinical relevance of mSEPT9 in colorectal cancer was explored by examining the correlation between Septin9 methylation levels and clinical characteristics using UALCAN and MethSurv software." (PMID 39466813, 2024). "To investigate the role of Septin9 in colorectal cancer, we utilized the TIMER2.0 database to analyze its differential expression between tumor tissues and adjacent normal tissues." (PMID 39466813, 2024). "The Septin 9 gene, encoding GTP-binding proteins, holds a pivotal role in the initiation and advancement of colorectal cancer (CRC), as indicated by previous research." (PMID 37892677, 2023). "QMSP has a wide range of clinical applications and is effective in testing aberrant methylation in the early diagnosis of tumors, such as methylated Septin9 (mSEPT9) in colorectal cancer or mRNF180 with mSEPT9 in gastric cancer." (PMID 37840147, 2023). "For example, promoter methylation of the gene Septin 9 (SEPT9/ SEPTIN9) is a plasma derived biomarker for colorectal cancer and is being studied for HCC27,44." (PMID 35798798, 2022). "The clinical utility of plasma methylated septin 9 (mSEPT9) DNA in screening and recurrence monitoring for colorectal cancer (CRC) is highly promising." (PMID 35818587, 2022). "The detection rate of methylated Septin9 (mSEPT9) in colorectal cancer (CRC) is varied greatly across the studies." (PMID 35546391, 2022). "This makes disease-specific DNA methylation a potential biomarker for various diseases, for instance, septin 9 (SEPT9)-methylated DNA for colorectal cancer screening." (PMID 34439828, 2021). "SEPT9, a gene that encodes SEPTIN9, is hypermethylated in colorectal cancer and is being proposed for non-invasive screening purposes." (PMID 34611479, 2021). "Methylated septin 9 (SEPT9) has been approved for non-invasive screening of colorectal cancer (CRC), but data on monitoring of CRC is sparse." (PMID 34873218, 2021). "In our previous research, we found that the DNA methylation rate of four molecular markers SNCA, SPG20, FBN1 and septin-9 had significant differences when colorectal cancer, colorectal adenoma and normal mucosa were compared." (PMID 33613751, 2021). "Even though the use of liquid biopsies for cancer screening is still largely undeveloped, a liquid biopsy test based on the detection of abnormal methylation of the SEPTIN9 gene in blood has already been approved to screen for colorectal cancer (CRC)." (PMID 33673461, 2021). "Prior studies demonstrated that Septin 9 was hypermethylated in a broad spectrum of tumors such as colorectal cancer, breast cancer, and cervical cancer." (PMID 32454907, 2020).
colorectal cancer (continued). "Septin 9, a well-established biomarker for colorectal cancer that is hyper-methylated in several cancers, is upregulated by EBV BART lncRNA." (PMID 31696060, 2019). "This includes a discussion of septin-9 (SEPT9) DNA hypermethylation for detecting colorectal cancer, which is by far the most developed epigenetic biomarker assay." (PMID 29614786, 2018). "Methylated Septin9 (mSEPT9) has been suggested as a reliable biomarker in colorectal cancer (CRC) detection." (PMID 30013949, 2018). "For example, reports show the translocation of the mixed lineage leukemia (MLL) oncogene into a septin gene locus and in colorectal cancer, septin 9 (SEPT9) exhibits an altered pattern of isoform expression." (PMID 29100341, 2017). "Overexpression of Septin 9 was widely detected in tumors and SEPT9 is now considered a biomarker for early detection of colorectal cancer." (PMID 26788989, 2016). "Hypermethylation of SEPTIN9 has been observed also in colorectal cancer (CRC) and a commercially available assay for that marker has been developed by the Epigenomics company, affording a sensitivity of 70 % for a specificity of 81 %." (PMID 27586786, 2016). "The short stature homeobox 2 (SHOX2) and septin 9 (SEPT9), for instance, are employed as diagnostic and screening tools for the detection of lung cancer and colorectal cancer." (PMID 27835597, 2016). "Determination of methylated Septin 9 (mSEPT9) in plasma has been shown to be a sensitive and specific biomarker for colorectal cancer (CRC)." (PMID 25526039, 2014). "Subsequently, a new blood-based colorectal cancer-specific test, the methylated Septin 9 (SEPT9) test, was developed." (PMID 23049919, 2012). "Methylated Septin 9 (SEPT9) is a sensitive biomarker for colorectal cancer (CRC) from peripheral blood." (PMID 23049919, 2012). "Studies on colorectal cancer have identified that methylation of the septin 9 gene occurs during carcinogenesis and is released into the plasma, which leads to the development of blood-based septin 9 gene methylation assays." (PMID 37256650, 2023). "Abnormal methylation of septin 9 (SEPT9) is one of the most frequently reported events, and the SEPT9 methylation test has already been approved by the Food and Drug Administration in early screening for colorectal carcinoma." (PMID 31191746, 2019). "In the clinical practice, nowadays, a few methylation markers are validated, such as septin 9 (SEPT9) in colorectal cancer, and several groups have reported that the analysis of circulating methylated tumor suppressor genes could be used for the non-invasive detection of human tumors, including HCC." (PMID 31694149, 2019). "The PCR-based Septin9 methylation assay, approved for early detection of colorectal cancer (CRC) in the USA, Europe, and China, measures plasma methylation levels of a CpG-rich fragment located in the Septin9 gene promoter." (PMID 39080571, 2024). "Our study showed that SNCA, SPG20, Septin9, and FBN1 can be used for colorectal cancer screening 11-12." (PMID 33613751, 2021). "In colorectal cancer (CRC), for instance, a blood-based screening was realized by targeting Septin 9 (SEPT9) hypermethylation, whose Epi proColon® test has been approved by the FDA in 2016." (PMID 32046186, 2020). "Septin 9 (SEPT9) and short stature homeobox 2 (SHOX2) methylation in circulating cell-free DNA (ccfDNA) are powerful biomarkers for colorectal cancer (CRC) screening, as well as head and neck squamous cell carcinoma staging and monitoring." (PMID 29610456, 2018). "Plasma methylation of Septin 9 is now available as a commercial test (Epi proColon 2.0; Epigenomics AG, Berlin, Germany) which has recently obtained FDA approval for colorectal cancer screening (April 2016)." (PMID 29061138, 2017). "Circulating methylated SEPTIN 9 (SEPT9) DNA and INTERMEDIATE FILAMENT FAMILY ORPHAN 1 (IFFO1) DNA in plasma were found to correlate with the occurrence of colorectal cancer and ovarian cancer, respectively." (PMID 23950870, 2013).
colorectal cancer (continued). "Methylation of Septin9 in peripheral blood is the first blood DNA methylation marker approved by the US Food and Drug Administration (FDA) for CRC screening, and is now widely used as a colorectal cancer biomarker." (PMID 35721189, 2022). "Some DNA methylation biomarkers such as Septin9 (SEPT9), Secreted frizzled- related protein 2 (SFRP2), and Syndecan 2 (SDC2) from blood or stool have been considered as feasible biomarkers for early detection of colorectal cancer." (PMID 35754025, 2022). "Hypermethylation of Septin 9 was initially described in colorectal cancer but not in normal tissue, which serves as a noninvasive screening test in plasma for colorectal cancer." (PMID 32454907, 2020). "Epi proColon® based on methylated septin 9 which is altered in colorectal cancer tumor cells more often than in normal cells is the first and only FDA-approved blood-based test the detection of colorectal cancer." (PMID 30953539, 2019). "However, specific or sensitive blood-based tumor markers, such as PSA for prostate cancer or Septin 9 methylated DNA for colorectal cancer, has yet not been identified in lung cancer." (PMID 31357969, 2019).
breast carcinoma (37 papers, 2011 to 2025). "The SEPT9 gene codes for Septin 9, a protein involved in cytokinesis and cell cycle control that has been implicated in early breast cancer development." (PMID 33113958, 2020). "Furthermore, methylation of the Septin9 promoter has recently been associated with cancer recurrence and metastasis phenomena, particularly in breast cancer." (PMID 39223638, 2024). "SEPTIN9 plays a role in multiple cancers including ovarian, prostate and breast cancer as either an oncogene or a tumor suppressor gene." (PMID 27586786, 2016). "SEPTIN9 was mapped to a region of loss of heterozygosity (LOH) at chromosome 17q25.3 in some cases of sporadic ovarian and breast cancer." (PMID 22479503, 2012). "SEPTIN9 functions as a putative breast and ovarian cancer tumor suppressor whose gene products (different mRNA isoforms) have been linked to increased cell migration and ECM degradation in breast cancer models." (PMID 38830843, 2024). "SEPTIN9 has been widely studied in cancer, and the overexpression of SEPTIN9, especially in breast cancer, suggests that it may have an important effect in cell proliferation and division." (PMID 39682314, 2024).
adenoma (22 papers, 2008 to 2025). A neoplasm arising from the epithelium. "Same as mutation markers, relative methylation level of Septin9, NDRG4, and BMP3 in CRC samples were higher than adenoma and NED groups, consistently in training and validation data sets." (PMID 33718241, 2021). "Comparing the three sample groups, tissue from NED patients showed significantly levels of Septin-9 protein than those from adenoma or cancer, and the detectable protein level in the latter two groups was similarly low." (PMID 25526039, 2014). "The level of Septin-9 protein in tissues was inversely correlated to mSEPT9 levels with abundant expression in normals, and diminished expression in adenomas and tumors." (PMID 25526039, 2014). "The decreased levels of Septin-9 protein expression in tissue samples of adenoma and cancer patients confirmed our findings published in a previous study." (PMID 25526039, 2014). "Our results from the IHC analysis of the different tissues indicated a significant reduction of epithelial Septin-9 protein levels in adenoma and tumor tissue." (PMID 23988185, 2013). "IHC data indicated a significant decrease (p <0.01) in Septin-9 protein levels in epithelial cells derived from adenoma and tumor tissues; Septin-9 protein levels in stromal cells were low in all tissues." (PMID 23988185, 2013). "Thus a tendency of weakening immunodetection of Septin-9 was observed along the adenoma-carcinoma sequence of disease progression." (PMID 25526039, 2014). "It is tempting to speculate that the increase in SEPT9 methylation of CGI3 in adenoma and tumor samples is directly responsible for the reduced Septin-9 expression levels." (PMID 23988185, 2013). "It is interesting to note that the levels of Septin-9 protein and those of mSEPT9 show an inverse correlation: high levels of Septin-9 protein correspond to low levels of mSEPT9 in the NED group, and vice versa in both adenoma and cancer." (PMID 25526039, 2014). "In adenoma and tumor samples, the epithelial Septin-9 level was not different from that found in stromal cells." (PMID 23988185, 2013).
prostate carcinoma (22 papers, 2014 to 2025). A carcinoma that arises from epithelial cells of the prostate gland. "Contrary to the finding in the current study that Septin4 can promote apoptosis by reducing HIF-1α levels in cardiomyocytes, it has been reported that other proteins in the Septin family like Septin9, can promote tumorigenesis by stabilizing HIF-1α levels in human prostate cancer cells." (PMID 34230460, 2021).
lung carcinoma (21 papers, 2008 to 2025). "The positive detection rates of each marker in lung carcinomas ranked from high to low were 69.1% (HOXA9), 64.7% (SHOX2), 45.6% (RASSF1A), 30.9% (cytology), and 20.6% (SEPTIN9)." (PMID 36176402, 2022). "In conclusion, we found that the aberrant promotor methylation of OncoMe (SHOX2, RASSF1A, SEPTIN9 and HOXA9) is a cancer-specific alteration and may be a valuable marker to aid in the differentiation of MPE, even not limited to lung cancer." (PMID 36176402, 2022). "Septin 9 (SEPT9), which belongs to the septin family and is involved in cytokinesis and cell cycle control, has been studied in many cancers including ovarian cancer, lung cancer, and CRC11–14." (PMID 34873218, 2021).
colon cancer (19 papers, 2011 to 2025). "In 2016, the FDA approved the first blood-based screening test, Epi proColon, that possibly detects the promoter methylation status of the septin 9 (SEPT9) gene in cell-free DNAs (cfDNAs) for colon cancer using qPCR." (PMID 34638288, 2021). "However, only the methylation of septin-9 (SEPT9) was translated into clinical application for screening colon cancer approved by the FDA in 2016, with variable values of sensitivity (58–95.6%) and specificity (69–97.1%)." (PMID 35974349, 2022). "Accordingly, both technologies reported the overexpression of STIM1, MBP, SEPTIN9, and SEPTIN10 and the downregulation of CRACR2A, ORMDL3, SARAF, SEPTIN3, and SEPTIN6 in colon cancer cells." (PMID 36900391, 2023).
gastric cancer (16 papers, 2016 to 2025). A primary or metastatic malignant neoplasm involving the stomach. "For example, methylation detection of the RNF180/Septin9 gene has shown significant advantages in the early screening of gastric cancer." (PMID 40244232, 2025). "For instance, the RNF180/Septin9 gene methylation test is applicable for early screening of gastric cancer." (PMID 40244232, 2025). "Moreover, combining the detection of RNF180 and Septin9 gene methylation with traditional tumor markers can significantly enhance the sensitivity of gastric cancer screening." (PMID 40244232, 2025). "The 2023 Chinese Expert Consensus on Early Gastric Cancer Screening and Testing Techniques states that RS19 gene methylation, combined with RNF180 and Septin9, can be used for the detection of early gastric cancer, suggesting that positive subjects should undergo gastroscopy in a timely manner." (PMID 39766341, 2024).
cervical cancer (15 papers, 2019 to 2025). A primary or metastatic malignant neoplasm involving the cervix. "Our previous project also confirmed that methylated Septin 9 gradually increased from cervical benign lesions, low/high-grade squamous intraepithelial lesions to cervical cancer (manuscript being submitted)." (PMID 32454907, 2020). "In addition to regulating the pathobiology of cervical cancer, promoter hypermethylation of Septin-9 (SEPT9) is a potential biomarker for early detection of the disease." (PMID 34685645, 2021). "Thus, we speculated that hypermethylation of Septin 9 may occur in the early stage of human cancers such as cervical cancer and NPC that contribute directly to cancer onset and progression." (PMID 32454907, 2020).